DPPA3 (developmental pluripotency associated 3)
Description:
Primordial germ cell (PGCs)-specific protein involved in epigenetic chromatin reprogramming in the zygote following fertilization. In zygotes, DNA demethylation occurs selectively in the paternal pronucleus before the first cell division, while the adjacent maternal pronucleus and certain paternally-imprinted loci are protected from this process (By similarity). Participates in protection of DNA methylation in the maternal pronucleus by preventing conversion of 5mC to 5hmC: specifically recognizes and binds histone H3 dimethylated at 'Lys-9' (H3K9me2) on maternal genome, and protects maternal genome from TET3-mediated conversion to 5hmC and subsequent DNA demethylation (By similarity). Does not bind paternal chromatin, which is mainly packed into protamine and does not contain much H3K9me2 mark (By similarity). Also protects imprinted loci that are marked with H3K9me2 in mature sperm from DNA demethylation in early embryogenesis (By similarity). May be important for the totipotent/pluripotent states continuing through preimplantation development (By similarity). Also involved in chromatin condensation in oocytogenesis (By similarity).
Synonyms: Stella; Pgc7
Tractability: No criterion of Open Targets' tractability assessment is met for any kind of drug.
Gene: Protein-coding gene on chromosome 12 (7,711,402 to 7,717,561, forward strand). Ensembl gene ENSG00000187569.
Subcellular location: Nucleus; Cytoplasm
Pathways (Reactome):
Developmental Biology: Chromatin modifications during the maternal to zygotic transition (MZT)
Gene Ontology:
Molecular function: protein binding; histone H3K9me2/3 reader activity
Biological process: epigenetic programing of female pronucleus
Cellular component: cytoplasm; nucleus; female pronucleus; male pronucleus
Genetic constraint (gnomAD): Loss-of-function variants: 9 observed, 14.11 expected, observed/expected ratio (o/e) 0.64, 90% interval 0.38 to 1.11. The upper end of that interval is the gene's LOEUF score, 1.11, which puts it in group 4 of 6, group 1 being the genes least tolerant of losing a copy. Missense variants: 148 observed, 189.54 expected, observed/expected ratio (o/e) 0.78, 90% interval 0.68 to 0.89. Synonymous variants: 61 observed, 70.29 expected, observed/expected ratio (o/e) 0.87, 90% interval 0.7 to 1.07.
Homologues: Orthologues: chimpanzee DPPA3 (99% identical), macaque DPPA3 (79% identical), macaque COX14 (79% identical), rat AABR07048770.1 (36% identical), rat Dppa3 (36% identical), rat LOC120096971 (35% identical), rat AABR07015759.1 (34% identical), rat Dppa3l1 (34% identical), mouse Dppa3 (33% identical), dog DPPA3 (28% identical).
Diseases named in the same sentence as DPPA3 in open-access papers:
DPPA3 is named in the same sentence as 15 diseases in open-access papers, as found by Europe PMC text mining. Sharing a sentence is not in itself a finding about the gene and the disease. The quoted sentences say what the papers report.
seminoma (6 papers, 2015 to 2025). A radiosensitive malignant germ cell tumor found in the testis (especially undescended), and extragonadal sites (anterior mediastinum and pineal gland). "Among them, GDF3, NODAL, LEFTY1 /2, GAL, DPPA3, SOX2, DNMT3B /L, DPPA5, BCAT1, FGF2, PRDM14, ZIC3 and FZD7, while seminoma markers SOX17, cKIT and PRAME were downregulated." (PMID 26226633, 2015). "We found that DPPA3, AK3L1, DNMT3B and NODAL are hypermethylated at analyzed loci in seminomas and parental TCam-2 compared to TCam-2 in vivo 6w and the EC samples." (PMID 26226633, 2015). "Another study in seminomas indicates that the overexpression of PRAME and its interaction with Lin28A support pluripotency networks and expression of reprogramming markers, such as DPPA3, Nanog, Oct3/4, ZSCAN10, and PRDM14." (PMID 40961095, 2025). "The DPPA3 and XIST genes were hypermethylated in LT-PTCs as compared to d0-PTCs and seminomas, MGMT displayed a variable DNA methylation pattern between and within groups and the KIT promoter was stably hypomethylated in all groups including seminomas." (PMID 32176716, 2020). "Expression of typical seminoma markers (PRDM1/BLIMP1, SOX17, PRAME, TFAP2C) was also detectable in TCam-2-ΔSOX2/FOXA2 tumor tissues, in contrast to EC reprogramming factors (GDF3, DPPA3, DNMT3B, GAL), which could only be detected in 2102EP in vivo or reprogrammed TCam-2 cells." (PMID 31130628, 2019). "However, this current study could not observe signs of a seminoma‐to‐EC‐transition, since putative driver genes (NODAL, DNMT3B, DPPA3, and GAL) were rather downregulated upon co‐culture of TCam‐2 cells with TM components compared with TCam‐2 mono‐cultures." (PMID 35811571, 2022).
Azoospermia (4 papers, 2009 to 2022). Absence of any measurable level of sperm,whereby spermatozoa cannot be observed even after centrifugation of the semen pellet. "Among them, Dppa3 (also called Stella) is a marker for cell pluripotency, and Dazl (deleted in azoospermia-like) and Tex14 (testis expressed 14) represent the state of premeiotic stage of the cells." (PMID 23509752, 2013). "Expression of WT hUSP26 resulted in increased expression of Usp26, Usp9y, Dazl, and Dppa3, whereas induction of these genes by the azoospermia-associated USP26 L364F variant was not significantly different from control samples." (PMID 35857630, 2022).
germ cell tumor (2 papers, 2014 to 2015). A benign or malignant, gonadal or extragonadal neoplasm that originates from germ cells. "One of them, DPPA3 (Developmental Pluripotency Associated 3) is also associated with germ cell tumors." (PMID 26541675, 2015). "In humans DPPA3 is expressed mainly in germ cell tumors, but not in normal testes." (PMID 24738045, 2014).
hepatocellular carcinoma (2 papers, 2021 to 2023). A malignant tumor that arises from hepatocytes. "In this study, based on analysis of an in vitro hepatocyte differentiation model, the maternal factor PGC7 (also known as DPPA3, STELLA) was found closely associated with liver development and tumor differentiation in hepatocellular carcinoma (HCC)." (PMID 33500560, 2021).
liver cancer (2 papers, 2021 to 2023). An epithelial or non-epithelial malignant neoplasm that arises from the liver. "They found that high expression of PGC7/DPPA3, a member of the developmental pluripotency-associated protein family, can promote HCC cell dedifferentiation and maintain an epigenetic status suitable for liver progenitor cells, resulting in liver cancer metastasis and poor prognosis." (PMID 37745860, 2023).
Obesity (2 papers, 2023 to 2025). Accumulation of substantial excess body fat. "In obese female mice, reduced expression of the Stella (DPPA3/PGC7) protein in oocytes suggests impaired embryonic development as a mechanism linking maternal obesity to adverse offspring outcomes." (PMID 41374021, 2025).
male infertility (1 paper, 2022). The inability of the male to effect fertilization of an ovum after a specified period of unprotected intercourse. "This included Usp26 itself, Dazl, which encodes an RNA-binding protein that is essential for gametogenesis in both males and females, Usp9y, a Y-linked gene encoding a deubiquitylase associated with male infertility and Dppa3, a primordial germ cell (PGC)-specific protein." (PMID 35857630, 2022).
ovarian carcinoma (1 paper, 2016). A malignant neoplasm originating from the surface ovarian epithelium. "APOBEC1, APOBEC2 and DPPA3 mRNAs were not expressed or expressed at the detection limit in the ovarian cancer tissues of the herein investigated cohort of patients and therefore those variables were excluded from the univariate Cox regression and all subsequent analyses." (PMID 27527602, 2016).
teratocarcinoma (1 paper, 2023). A germ cell tumor characterized by the presence of an embryonal carcinoma component and a teratoma component. "In human, the chromosome region where NANOG is located also contains DPPA3, POU5F1P3 and another pluripotency factor, GDF3, and collectively is called a ‘hotspot for teratocarcinoma’ owing to the high rate of chromosomal abnormalities." (PMID 36621005, 2023).
cancer (7 papers, 2015 to 2025). A tumor composed of atypical neoplastic, often pleomorphic cells that invade other tissues. "Therefore, the present results imply that 12p gains may be indispensable for the development of ECs because 12p includes various genes associated with cancer (e.g., DPPA3, GDF3, KRAS, or CCND2)." (PMID 32999426, 2020). "In some cancer cells Dppa3 could also mediate demethylation by preventing Tet3 function." (PMID 35477484, 2022).
tumor (5 papers, 2019 to 2024). "A recent research showed that Dppa3 promotes tumor oncogenic dedifferentiation through remodeling DNA methylation state." (PMID 35477484, 2022). "In addition, metastatic tumor cells also specifically expressed some genes, such as DPPA3, NANOG, CRABP1 and others." (PMID 35494058, 2022).
DPPA3 also shares sentences with these, for which no sentence is quoted: breast carcinoma (2 papers); embryonal carcinoma (2); schizophrenia (1); uveal melanoma (1).